TREM1 (triggering receptor expressed on myeloid cells 1)
Description:
[Isoform 1]: Cell surface receptor that plays important roles in innate and adaptive immunity by amplifying inflammatory responses. Upon activation by various ligands such as PGLYRP1, HMGB1 or HSP70, multimerizes and forms a complex with transmembrane adapter TYROBP/DAP12. In turn, initiates a SYK-mediated cascade of tyrosine phosphorylation, activating multiple downstream mediators such as BTK, MAPK1, MAPK3 or phospholipase C-gamma. This cascade promotes the neutrophil- and macrophage-mediated release of pro-inflammatory cytokines and/or chemokines, as well as their migration and thereby amplifies inflammatory responses that are triggered by bacterial and fungal infections. By also promoting the amplification of inflammatory signals that are initially triggered by Toll-like receptor (TLR) and NOD-like receptor engagement, plays a major role in the pathophysiology of acute and chronic inflammatory diseases of different etiologies including septic shock and atherosclerosis. [Isoform 2]: Acts as a decoy receptor, counterbalancing TREM1 pro-inflammatory activity through the neutralization of its ligand.
Synonyms: TREM-1; CD354
Tractability: Small molecule: a structure with a bound ligand is known; it has a high-quality binding pocket. Antibody: UniProt places it where antibodies can reach, with high confidence; its Gene Ontology location is reachable by antibodies, with high confidence; UniProt predicts a signal peptide or a membrane-spanning region. PROTAC: ubiquitination databases record sites on it. Other modalities: a drug acting on it is in phase 2 or 3 trials.
Target class: Membrane receptor
Gene: Protein-coding gene on chromosome 6 (41,267,100 to 41,286,682, reverse strand). Ensembl gene ENSG00000124731.
Subcellular location: Cell membrane (Isoform 1); Secreted (Isoform 2)
Subcellular location (Human Protein Atlas): Golgi apparatus; Predicted to be secreted
Pathways (Reactome):
Immune System: DAP12 interactions; Immunoregulatory interactions between a Lymphoid and a non-Lymphoid cell
Hemostasis: Cell surface interactions at the vascular wall
Gene Ontology:
Molecular function: scaffold protein binding; transmembrane signaling receptor activity; signaling receptor activity
Biological process: humoral immune response; intracellular signal transduction; neutrophil chemotaxis; neutrophil-mediated killing of gram-negative bacterium
Cellular component: cell surface; extracellular region; plasma membrane
Genetic constraint (gnomAD): Loss-of-function variants: 16 observed, 23.71 expected, observed/expected ratio (o/e) 0.67, 90% interval 0.46 to 1.02. The upper end of that interval is the gene's LOEUF score, 1.02, which puts it in group 4 of 6, group 1 being the genes least tolerant of losing a copy. Missense variants: 283 observed, 297.98 expected, observed/expected ratio (o/e) 0.95, 90% interval 0.86 to 1.05. Synonymous variants: 110 observed, 118.23 expected, observed/expected ratio (o/e) 0.93, 90% interval 0.8 to 1.09.
Homologues: Orthologues: chimpanzee TREM1 (99% identical), macaque TREM1 (82% identical), dog TREM1 (54% identical), pig TREM1 (51% identical), rat Trem1 (47% identical), mouse Trem1 (45% identical), guinea pig Trem1 (40% identical).
Diseases named in the same sentence as TREM1 in open-access papers:
TREM1 is named in the same sentence as 315 diseases in open-access papers, as found by Europe PMC text mining. Sharing a sentence is not in itself a finding about the gene and the disease. The quoted sentences say what the papers report.
Sepsis (154 papers, 2007 to 2026). Sepsis is defined as life-threatening organ dysfunction caused by a dysregulated host response to infection. "TREM-1 and its soluble variant sTREM-1 rise in sepsis and chronic inflammatory states and appear to amplify inflammatory signals." (PMID 41273150, 2026). "Recent studies for the past three years have investigated the performance of Gal-9 for predicting the risk of malignancy in dermatomyositis, prognostic value of TREM-1 in sepsis, and diagnostic value of sCD25 for discriminating neonatal sepsis." (PMID 41225969, 2025). "Currently, TREM-1 is widely recognized as a critical contributor to the immune dysfunction caused by sepsis." (PMID 41404075, 2025). "Lowers TNF-α and IL-1β serum levels, serves as a diagnostic and prognostic tool, and neutralizes TREM-1 while activating monocytes in sepsis patients." (PMID 41226426, 2025). "In a subset of sepsis samples, patient sera activate monocytes ex vivo, and this response is specifically blocked by TREM-1-Fc, indicating that soluble or cell-associated TREM-1 ligands contribute to monocyte activation in these cases." (PMID 41226426, 2025). "Overactive TREM-1 signaling has been associated with conditions such as sepsis, acute lung injury, inflammatory bowel disease, rheumatoid arthritis, and inflammation related to cancer." (PMID 41226426, 2025). "The circulating levels of the cleaved soluble extracellular portion of TREM-1 (sTREM-1) are elevated in patients with sepsis and associated with increased mortality in patients with septic shock." (PMID 38191420, 2024). "Blocking TREM-1 signaling has been explored as a potential approach to the treatment of inflammation-associated disorders, including sepsis, rheumatoid arthritis, and retinal neovascularization, as well as cancer." (PMID 39418109, 2024). "Upregulation of TREM-1 on immune cells is implicated in acute inflammation, while sustained TREM-1 activation plays a crucial role in sepsis, arthritis, and colitis." (PMID 39418109, 2024). "Mice deficient in endothelial TREM-1 or treated with a TREM-1 inhibitor were protected against endothelial dysfunction in sepsis." (PMID 36246143, 2022). "Next, soluble TREM-1, the extracellular domain of TREM-1 that is cleaved and released into circulation during sepsis and sepsis-associated AKI and serves a marker of TREM-1 activation, was evaluated in the serum and urine." (PMID 36246143, 2022). "Soluble TREM-1 (sTREM-1) expression was found to be upregulated in sepsis-associated acute kidney injury (SA-AKI) and predicted to be a potential biomarker." (PMID 33390769, 2021). "Variants present in the TREM1 gene are associated with susceptibility to inflammatory bowel diseases, sepsis prognosis, pneumonia, coronary artery disease, septic shock, severe malaria and atherosclerosis." (PMID 33924130, 2021). "This inflammation was originally thought to be entirely TLR4 dependent, however evidence is growing that TREM-1 is important in sepsis-associated cardiac inflammation." (PMID 33276725, 2020). "In vivo, TREM-1 was first identified in sepsis and suggested to be an important diagnostic/prognostic marker in both bacterial and fungal infections." (PMID 32456204, 2020). "The aim of our study was to investigate the impact of a genetic variant of the TREM-1 gene, which is located on chromosome 6, on the survival of patients with sepsis." (PMID 30832396, 2019). "Because the blockade of TREM-1 protected mice against lipopolysaccharides-induced shock and sepsis was caused by Escherichia coli, this receptor was suggested as a potential therapeutic target." (PMID 29282483, 2018). "Neutrophils from elderly patients have been found to respond poorly following TREM-1 engagement, suggesting possibly an important intrinsic cause of the higher incidence of sepsis-related deaths in this sector of the population." (PMID 29064819, 2017).
Sepsis (continued). "Urine soluble triggering receptor expressed on myeloid cells-1 (sTREM-1) has been reported in sepsis diagnosis and prediction of sepsis-associated acute kidney injury (AKI)." (PMID 26169055, 2015). "Among the ERGs, we found several suggested prognostic and diagnostic sepsis markers, including triggering receptor expressed on myeloid cells 1 (TREM1) and microRNA miR233." (PMID 25706641, 2015). "Triggering receptor expressed on myeloid cells-1 (TREM-1) was reported to be upregulated in various inflammatory diseases as well as in sepsis; TREM-1 expression is associated with elevations in soluble TREM-1 (sTREM-1)." (PMID 24772418, 2014). "The results of the present study demonstrate a major role of TREM-1 in acute septic process; a decrease in monocyte gene TREM-1 expression during the first 3 days of sepsis is associated with worse outcome." (PMID 25532536, 2014). "In sepsis patients Trem-1 expression on neutrophils was associated with the IL-10 (LPS: r = 0,61, p < 0.02) and TNF-α inducibility (LPS: r = 0,78, p < 0,002)." (PMID 23414215, 2013). "Trem-1 on blood neutrophils is tendentially lower in patients with severe sepsis, associated with reduced cytokine inducibility." (PMID 23414215, 2013). "Patients with E. coli sepsis are characterized by an association of Trem-1 expression on blood neutrophils with cytokine inducibility." (PMID 23414215, 2013). "Decrease of the expression of TREM-1 on the membrane of monocytes and neutrophils upon transition from sepsis to severe sepsis/septic shock depends on the underlying type of infection and the causative pathogen." (PMID 22050935, 2011). "More precisely, expression of TREM-1 was decreased when severe sepsis/shock developed in the field of infections caused by Gram-negative community-acquired bacteria." (PMID 22050935, 2011). "The present study aimed at the role of underlying infection and of the causative pathogen in the expression of TREM-1 in sepsis." (PMID 22050935, 2011). "For example, levels of soluble triggering receptor expressed on myeloid cells-1 (sTREM-1), which are elevated in patients with sepsis and have been associated with poor outcomes, were used in a phase 2 trial of nangibotide, a TREM-1 inhibitor, in patients with septic shock." (PMID 41157190, 2025). "TREM-1 exhibits temporally dynamic induction and has been implicated in diverse pathologies, including ischemic stroke, subarachnoid hemorrhage, spinal cord injury, migraine, myocardial infarction, inflammatory bowel disease, and sepsis." (PMID 40761800, 2025). "(2013) showed that low TREM-1 expression in neutrophils may be associated with hyporesponsiveness during severe sepsis." (PMID 35402286, 2022). "It has been shown that TREM1 is a promising diagnostic biomarker and therapeutic target for sepsis." (PMID 33954188, 2021). "Interestingly, genetic variants within the gene encoding TREM-1 are associated with different levels of inflammation and with the development of sepsis and severe malaria in which sTREM-1 levels were high." (PMID 34960790, 2021). "This study aimed to determine whether the functional TREM-1 rs2234237 single nucleotide polymorphism was associated with mortality in a cohort of 649 Caucasian patients with sepsis." (PMID 30832396, 2019). "Soluble TLT-1 could be thus of therapeutic use against sepsis associated inflammation by down regulating the effect of TREM-1 in the immune response." (PMID 26967520, 2016). "The TREM superfamily also includes a sepsis-associated TREM1 and a soluble form of TREM2 which may extend TREM2 activities well beyond the cells in which they were initially generated." (PMID 26949937, 2016). "A reciprocal decrease of the pro-inflammatory surface receptor TREM-1 linked with sepsis-induced immunosuppression may be part of the explanation." (PMID 25532536, 2014). "Low Trem-1 expression on neutrophils might be associated with hyporesponsiveness during severe human sepsis." (PMID 23414215, 2013).
Sepsis (continued). "Missing identification of the exact ligand for TREM-1 creates the hypothesis that TREM-1 expression on neutrophils and monocytes in sepsis may differ according to the type of infection causing sepsis and/or the type of implicated bacteria." (PMID 22050935, 2011). "TREM‐1 is a receptor constitutively expressed on neutrophils and monocyte subsets, linked to inflammatory response in infections or non‐infectious inflammatory pathologies, such as sepsis and rheumatoid arthritis, and it can also be produced in its soluble form (sTREM‐1)." (PMID 37601842, 2023). "Therefore, animal or cell experiments (or both) are necessary to confirm whether the use of TREM-1 inhibitors could block the process of sepsis-associated renal local inflammatory immune status." (PMID 26169055, 2015). "Soluble triggering receptor expressed on myeloid cells 1 (sTREM-1) has been identified as a crucial marker in sepsis, connecting the activation of innate immunity to systemic inflammation." (PMID 41273150, 2026). "The correlation between elevated sTREM-1 levels and decreased TREM-1 expression on monocytes and neutrophils underscores the intricate dynamics of systemic and cellular immune responses in sepsis and septic shock." (PMID 41273150, 2026). "Conversely, TREM1 expression on neutrophils declined in patients with sepsis and septic shock, suggesting a potential regulatory adaptation or consumption mechanism associated with infection severity." (PMID 41273150, 2026). "Soluble triggering receptor expressed on myeloid cells 1 (sTREM-1) has emerged as a biomarker, amplifying the immune response in sepsis and linking innate immunity activation to the systemic inflammation characteristic of this condition." (PMID 41273150, 2026). "Recent research indicates that dysregulated TREM-1 signaling contributes to the pathogenesis of several inflammatory diseases, such as sepsis, myocardial infarction, atherosclerosis, and ischemic stroke." (PMID 41226426, 2025). "In neonatal sepsis with myocardial dysfunction, CIRP interaction with TREM-1 increased inflammation, which showed that CIRP played a direct role in many of the mechanisms of sepsis-associated cardiac dysfunction in neonates." (PMID 39907066, 2025). "Studies investigating the effects of LR12 in sepsis, anti-atherosclerosis, lung disease, liver disorders, and other ailments have demonstrated its potent inhibition of TREM1 activity, leading to reduced inflammation and improved tissue or organ damage." (PMID 40011963, 2025). "Recently, extracellular actin derived from platelets has been identified as a novel ligand for TREM1 in the context of sepsis." (PMID 40011963, 2025). "The binding between eCIRP and TREM-1 can dramatically enhance inflammation during sepsis in macrophages and a peptide-mediated blocking of this interaction significantly improves the outcome, increasing the survival rate." (PMID 40948752, 2025). "Amplification of the inflammatory response by TREM-1 is considered a critical contributor to the dysregulated immune response in sepsis." (PMID 41225969, 2025). "It has been reported that extracellular actin co-localizes with TREM-1 in lung tissue sections from septic mice, suggesting that TREM-1 recognizes actin during activation in sepsis." (PMID 40948752, 2025). "In this study, a strong dependence of TREM-1 inhibition efficacy on inhibitor specificity and timing of treatment initiation relative to challenge was observed in experimental sepsis." (PMID 41404075, 2025). "Although sTREM-1 attenuates excessive inflammatory response by counter-regulating TREM-1, inflammatory amplifier in sepsis, sLMIR-5 amplifies LPS-induced lethal inflammation." (PMID 40948752, 2025). "These insights support the therapeutic targeting of TREM-1, not only in acute infections and sepsis but also in inflammation-driven conditions such as atherosclerosis, fibrosis, and tumor progression." (PMID 41226426, 2025).
Sepsis (continued). "This process can provide a large number of ligands for activation of TREM-1 signalling and thus induce some progressive systemic inflammatory response, resulting in sepsis." (PMID 40948752, 2025). "The five tested biomarkers, IL6, IL8, TREM-1, suPAR, and presepsin, have previously been shown to be remarkable biomarkers of sepsis with pneumonia (Larsen and Petersen 2017)." (PMID 39857101, 2025). "This TREM1- NF-κB interaction represents a mechanism distinct from the parallel activation of TREM1 and TLR4 signaling observed in sepsis 38, suggesting a TBI-specific damage-associated molecular patterns co-recognition mechanism." (PMID 40963908, 2025). "TREM-1 has been studied in relation to clinical outcomes in sepsis and other inflammatory conditions." (PMID 41226426, 2025). "Here, GF9 and GA31-LPC were used to comparatively study pan-TREM-1 and macrophage-restricted TREM-1 blockades in animal models of pancreatic cancer, sepsis, pulmonary inflammation and fibrosis." (PMID 41404075, 2025). "Recent studies indicate that murine rCIRP exhibits high affinity (Kd = 120 nM) for recombinant murine TREM-1 (rmTREM-1), and inhibition of TREM-1 mitigates systemic and pulmonary inflammation in rCIRP-induced murine sepsis models." (PMID 41226426, 2025). "Trigger receptor-1 (TREM-1) expressed on myeloid cells plays a key regulatory role in the inflammatory cascade reaction during sepsis." (PMID 41209006, 2025). "Exaggerated inflammation mediated through TREM-1 activation is considered a critical contributor to the pathophysiology of sepsis through promoting release of inflammatory cytokines and chemokines." (PMID 38881893, 2024). "Since 2001, when the first blockade of TREM-1 in sepsis was performed, many potential TREM-1 inhibitors have been established in animal models." (PMID 38191420, 2024). "Nevertheless, many of the TREM-1 inhibitory peptides proposed for the treatment of sepsis are based on amino acid sequences found in sTREM-1." (PMID 38191420, 2024). "In LPS-, CLP-, and E. coli–induced sepsis, mice had improved survival rates due to TREM-1/Fc treatment." (PMID 38191420, 2024). "Peptide-based therapies such as LP17, M3, and N1 bind to TREM-1, reducing inflammatory responses and demonstrating therapeutic effects in various sepsis models induced through different methods." (PMID 39081318, 2024). "Sepsis presents a dysregulated immune response, and TREM-1 has attracted attention as a potential contributor to this condition that often ends in death." (PMID 38191420, 2024). "Because patients with sepsis and septic shock show elevated sTREM-1 levels, TREM-1 has attracted attention as an important contributor to the inadequate immune response in this often-deadly condition." (PMID 38191420, 2024). "A2M, IL1F10, SYT13, and TREM1 emerge as compelling biomarkers for sepsis and trauma based on their distinct roles in immune response modulation." (PMID 38283341, 2023). "The prognostic value of TREM-1 in particular for Streptococcus progenies-induced sepsis was investigated in both mouse models and patients." (PMID 37456011, 2023). "TREM-1 is a receptor expressed on neutrophils and monocytes that modulates the inflammatory response, and is upregulated in sepsis." (PMID 37606991, 2023). "M3 exerts protective effects against sepsis-induced myocardial injury and acute kidney injury after renal I/R by inhibiting the eCIRP/TREM-1 interaction." (PMID 36865547, 2023). "This is supported by a recent experimental study showing that TREM-1 regulates nitric oxide release by endothelial cells in sepsis, and mesenteric artery sensitivity to phenylephrine in ex vivo experiments." (PMID 37522081, 2023). "The plasma levels of soluble TREM-1 (sTREM-1) are able to differentiate sepsis from systemic inflammatory response syndrome; within sepsis, survivors show lowered levels of sTREM-1 whereas non-survivors do not." (PMID 37456011, 2023).